IL6 (interleukin 6)
Diseases named in the same sentence as IL6 in open-access papers (continued):
Sharing a sentence is not in itself a finding about the gene and the disease.
COVID-19 (continued). "Another study focused on identifying the strongest predictive factors of COVID-19 mortality found that, compared with their overall cohort, mortality was significantly higher in severely ill old patients with IL-6 >/= 33 pg/mL at baseline." (PMID 40333142, 2025). "Elevated levels of pro-inflammatory cytokines, such as interleukin-6 (IL-6) and tumor necrosis factor-alpha (TNF-α), have been associated with severe COVID-19 outcomes." (PMID 40002822, 2025). "We determined the association between LTBi positivity with severity of COVID-19 as well as mRNA expression of immune related genes including those required for MTB as well as SARS-CoV-2 control; IFN-γ, IFN-α, IL-6, IL-10, OAS1, MAVS, SOCS1 and SOCS3 molecules." (PMID 41468475, 2025). "The effect size was larger than that seen in COVID-19 and coronary artery disease, where interleukin-6 inhibition has been successful in trials." (PMID 40819633, 2025). "Regarding the theory that differential systemic inflammation or endothelial activation due to ABO blood type, a wealth of studies have been published on the association between inflammation, hypercytokinemia (specifically IL-6) and outcomes in COVID-19." (PMID 40173171, 2025). "Diabetes mellitus was in significant positive correlation with the IL-6 of COVID-19 female patients." (PMID 40868247, 2025). "This three-way interaction between IL-6, zinc, and infection makes it difficult to assess the impact of these biomarkers in the context of COVID-19 severity." (PMID 40756075, 2025). "COVID-19 mRNA vaccines activate NF-κB, which stimulates the production of various cytokines such as IL-6." (PMID 40733655, 2025). "Serum from patients with severe COVID-19 induced increased levels of IL-1α, IL-1Ra, IL-5, IL-6, IL-10, IL-12(p40), IL-18, IL-27, and TNF-α." (PMID 41583455, 2025). "In most studies conducted in Asia and Europe, circulating IL-6 levels correlate with COVID-19 severity." (PMID 40508859, 2025). "Elevated IL-6 levels and higher NLR values are associated with reduced FMD, suggesting their role in endothelial dysfunction among post-COVID-19 patients." (PMID 40143236, 2025). "Specifically, C-reactive protein (CRP) was elevated in 22.7% of cases, interleukin-6 (IL-6) in 13.6%, and ferritin in 18.2%, consistent with the hyperinflammatory response seen in COVID-19-related cytokine storms." (PMID 40091918, 2025). "A narrative review by Eljilany and Elzouki similarly emphasized that D-dimer, fibrinogen, and IL-6 are useful for flagging a prothrombotic state but are insufficient as stand-alone prognostic tools for VTE-related outcomes in COVID-19." (PMID 41463074, 2025). "A recent study in solid-organ transplant recipients (SOTRs) with COVID-19 found a strong correlation between monocyte-derived cfDNA and pro-inflammatory cytokines, including IL-6 and IL-18." (PMID 40788382, 2025). "AGP, another acute-phase protein, is upregulated in severe COVID-19, and correlates with IL-6 and C-reactive protein levels, underscoring its involvement in cytokine storm pathogenesis." (PMID 40284260, 2025). "While IL-6 blockade has shown promise in conditions like rheumatoid arthritis and COVID-19 (The REMAP−CAP Investigators, 2021)." (PMID 40692679, 2025). "CRP (Mann–Whitney U = 24655, p = 0.008), IL-6 (Mann–Whitney U = 12010, p = 0.0003), and ferritin (Mann–Whitney U = 7585, p < 0.0001) were largely increased in severe COVID-19 male patients." (PMID 40868247, 2025). "It is likely that the IL-6 feedback loop and cytokine storm in COVID-19 are enhanced by complement pathways." (PMID 40552181, 2025). "High IL-6 levels have been linked to acute respiratory distress syndrome (ARDS), a hallmark of severe COVID-19, which requires extended hospitalization and often mechanical ventilation." (PMID 40137715, 2025).
COVID-19 (continued). "Biological therapies, such as TNF inhibitors, IL-6 inhibitors, and other targeted agents, are known to interfere with the dysregulated immune signaling that often occurs in severe COVID-19 and related complications." (PMID 40755909, 2025). "A study indicated that the inflammatory profile (CRP, IL-10, IL-17, IL-6, TNFα, and IL-1β) observed during the acute phase of severe COVID-19 predicts future long COVID symptoms." (PMID 40048451, 2025). "For example, therapeutic approaches aimed at neutralizing IL-6 during COVID-19 have shown promise in reducing the severity of cytokine storms and improving clinical outcomes." (PMID 39862905, 2025). "This has important prognostic significance in COVID-19, as the binding of IL-6 to the formed sIL-6R leads to interaction with gp130 receptors, which are presented on many cells (immune cells, epithelial cells, fibroblasts)." (PMID 40066463, 2025). "An early and temporary inflammatory cytokine response characterized by elevated levels of IFN-γ, GIP-10, IL-6, and C-reactive protein was detected on day 2 after receiving the BNT162b2 mRNA (Pfizer/BioNtech) COVID-19 vaccine." (PMID 40525031, 2025). "Based on current knowledge, we challenged the ratio of two COVID-19 pivotal biomarkers (interleukin 6 and Krebs von den Lungen 6 protein) to match this goal." (PMID 40397955, 2025). "For example, IL-6 concentrations in COVID-19 average around 36.7 pg/mL, compared with nearly 100-fold higher levels in CAR-T cell–induced cytokine release syndrome and even higher levels in sepsis and ARDS." (PMID 41158128, 2025). "IL-6 and IL-10 levels were significantly elevated in COVID-19 patients suffering from pneumonia or organ failure." (PMID 41585373, 2025). "In reports related to COVID-19, elevated levels of IL-6 are considered a predictive parameter for poor disease progression and the need for invasive oxygen support." (PMID 39968105, 2025). "In COVID-19, severe outcomes have increased levels of pro-inflammatory and anti-inflammatory cytokines and chemokines, such as IL-6, TNF-α, IL-10, CCL2, CCL3, CXCL8, and CXCL10, among others." (PMID 40881695, 2025). "IL-6 inhibitors such as tocilizumab have demonstrated protective effects in early stages of COVID-19 against later development of depressive symptoms." (PMID 41323348, 2025). "Collectively, these results support the potential of IL-17 as a complementary biomarker—acting synergistically or independently of IL-6—for early prediction of severe COVID-19 or post-COVID inflammatory syndromes." (PMID 41184328, 2025). "We encourage the same analysis of IL-6 kinetics for larger cohorts of patients in the same stages of COVID-19." (PMID 39210228, 2025). "Concurrently, interleukins like IL-6, IL-8, IL-10, IL-17, and IL-1β are vital mediators of inflammation and have been shown to correlate with the severity of the disease in COVID-19 cases." (PMID 41585373, 2025). "When laboratory data were compared according to COVID-19 severity, IL-6, IL-6/IL-10 ratio, and miR-155 expression showed the highest values in the severe group while serum IL-10 reached its lowest level in the severe group." (PMID 41203712, 2025). "This aligns with previous studies showing increased serpins, including AAT, in COVID-19 sera, particularly in patients with high Interleukin-6 levels, and evidence suggesting that AAT deficiency increases the risk of severe COVID-19." (PMID 39949890, 2025). "Antiviral drug GS-5734 (remdesivir) administration with anti-inflammatory therapy reduces the TMPRSS2 blood level in moderate COVID-19, IL-6 in severe COVID-19 course, and fibrinogen A- and D-dimers in both groups." (PMID 40573382, 2025). "COVID-19 is characterized by a dysregulated immune response, leading to the excessive release of pro-inflammatory cytokines such as IL-1β, IL-6, and TNF-α, which contribute to tissue injury and multiorgan dysfunction." (PMID 40710798, 2025).
COVID-19 (continued). "A randomized, double-bind, placebo-controlled, parallel trial revealed that additional oral arginine supplementation in patients with COVID-19 led to significantly reduced levels of pro-inflammatory IL-2, IL-6, and IFN-γ." (PMID 40332615, 2025). "Initially, we observed a high concentration of IL-6 and IL-1β in COVID-19 patients compared with controls, indicating disease severity in these patients (Supplementary data_Table S1)." (PMID 40709999, 2025). "A key aspect of severe COVID-19 is the overactive host-defence response, often called “cytokine storm,” Where cytokines that promote inflammation, like IL-6 and IL-10, significantly influence disease progression." (PMID 41585373, 2025). "In individuals with COVID-19, IL-6 is one of the key inflammatory mediators responsible for triggering the cytokine storm." (PMID 40806851, 2025). "Similar results were reported by Huang and colleagues, who reported increased circulating levels of IL-6 and IL-10 in critical COVID-19 patients." (PMID 40508859, 2025). "IL-6 is a crucial cytokine in the pathogenesis of hyperinflamed critically ill patients with sepsis, COVID-19, and the cytokine release syndrome (CRS) that a proportion of patients develop after receiving CAR-T cell therapy." (PMID 40117010, 2025). "In COVID-19, immune effector cells secrete high levels of chemokines and proinflammatory cytokines (e.g., TGFβ, TNFα, IL-33, IL-18, IL-12, IFNγ, IL-6, IL-1β, and IFN-α) in response to SARS-CoV-2 infection." (PMID 40002929, 2025). "This study identified significant associations between genetic variants in the IL1B, IL6, and TNF genes and the severity of clinical outcomes in COVID-19 patients." (PMID 40506975, 2025). "In COVID-19 cohorts, higher CRP concentrations have been tightly linked to elevated IL6 and to worse outcomes, including respiratory failure, intensive care unit (ICU) admission, and mortality." (PMID 41373577, 2025). "Currently, the most frequently used drugs for managing severe COVID-19 are immunomodulatory agents, including IL-6 inhibitors." (PMID 40794529, 2025). "Macrophages, as the innate immune cells is reported to contribute to the progression of COVID-19, by producing a large amount of interleukin 6 (IL-6)." (PMID 40300201, 2025). "Emerging evidence underscores that heightened values of IL-6 with other inflammatory cytokines closely correspond to adverse outcomes in COVID-19." (PMID 41585373, 2025). "Prior research has proposed a thromboinflammatory mechanism connecting liver injury in COVID-19 to endotheliopathy, potentially mediated by IL-6 trans-signaling and subsequent elevation of coagulation factors." (PMID 40364223, 2025). "In COVID-19 patients, IL-6 levels are significantly elevated and related to unfavorable clinical outcomes." (PMID 39940970, 2025). "CRP levels correlated positively with inflammatory cytokines, particularly IL-6, in COVID-19 patients and served as a biomarker for disease severity." (PMID 40333142, 2025). "In the context of COVID-19, a cytokine storm—characterized by elevated interleukin-6 (IL-6), tumor necrosis factor-alpha (TNF-α), and C-reactive protein (CRP)—has been proposed as a contributing factor to dyslipidemia." (PMID 40565828, 2025). "This metabolic adaptation fuels immune cell activation and cytokine production but can also lead to excessive inflammation, as seen in severe COVID-19 cases where IL-6 levels correlate with disease severity." (PMID 40453076, 2025). "In patients with COVID-19, the correlation between IL-6 as a marker of inflammation and OS was observed." (PMID 41415584, 2025). "Several biomarkers associated with COVID-19 progression and the onset of acute respiratory distress syndrome include elevated LDH, CR, IL-6, D-dimer levels, lymphocyte and platelet counts, renal function markers, and high-sensitivity troponin." (PMID 40283612, 2025).
COVID-19 (continued). "One study reported that 52% of COVID-19 patients exhibited elevated IL-6 levels, while 86% showed increased CRP, reflecting a significant inflammatory state." (PMID 40046064, 2025). "In the context of SARS-CoV-2 infection, the present study aimed to determine the clinical and laboratory characteristics and serum levels of IL-6 and zinc in patients with COVID-19 according to their clinical condition in a hospital in Lima, Peru." (PMID 40756075, 2025). "In this context, the association between genetic variants in the IL1B, IL6, and TNF genes and the severity of COVID-19 was explored, with particular emphasis on outcomes such as hospitalization, the need for ICU admission, and mortality." (PMID 40506975, 2025). "We found, as expected, that IL-6 levels in the COVID-19/Self-RPD+ group (26.8 pg/mL ± 43.4 pg/mL) were significantly higher than those in the COVID-19 only and Self-RPD+ groups (22.7 pg/mL ± 29.1 pg/mL and 16.6 pg/mL ± 14.9 pg/mL, respectively)." (PMID 40647649, 2025). "Markers of inflammation and tissue damage, such as CRP, IL-6, and novel biomarkers like suPAR and NETs, have provided significant insights into the pathophysiology of COVID-19." (PMID 40094929, 2025). "The high level of D-dimers, indicating an increased hypercoagulation, together with elevated levels of IL-6 and CRP, indicating sustained inflammation, are associated with an increase in infection, sepsis, and mortality in COVID-19 patients." (PMID 40149514, 2025). "Our data are concordant with other publications that suggest the relevance and importance of monitoring circulating levels of IL-6 and IL-10 as useful predictors of early diagnosis for severe COVID-19 patients." (PMID 40508859, 2025). "COVID-19's cytokine storm, characterised by IL-6, TNF-α, and IL-1β elevation, damages the neurovascular unit and increases vascular permeability." (PMID 41503306, 2025). "In patients with COVID-19, the production of GM-CSF initiates a positive feedback loop, leading to the overexpression of interleukin-6 (IL-6) and other proinflammatory factors, particularly by CD14+ and CD16+ inflammatory monocytes." (PMID 40821797, 2025). "We previously reported that inflammatory cytokines were increased in COVID-19 patients, while IL-6 was also elevated in vaccinated COVID-19 patients." (PMID 40868247, 2025). "Fibrosis and severe COVID-19 share overlapping cytokine profiles, including elevated TGFβ and IL-6 levels, which suggest shared mechanisms." (PMID 40299552, 2025). "In severe COVID-19, elevated levels of cytokines such as TNF-α, IL-6, IL-8, and IL-10 have been significantly associated with a reduction in T-cell counts." (PMID 41002992, 2025). "The analysis of inflammatory markers and hyperglycemia in COVID-19 patients revealed a correlation between IL-1 and IL-6 levels on the first day and elevated blood glucose levels." (PMID 40134446, 2025). "The progression of COVID-19 has been associated with elevated plasma levels of acute-phase reactants, including C-reactive protein (CRP), IL-6, D-dimer, and procalcitonin." (PMID 40869381, 2025). "In contrast, we found that other markers often used to measure inflammaging, including IL-6, IL-1b, and TNF-a, showed weaker associations with naïve T cells or odds of hospitalization or death from COVID-19." (PMID 41280118, 2025). "Elevated levels of pro-inflammatory cytokines, such as IL-6, IL-1β, and TNF-α, are consistently associated with disease progression and poor prognosis in COVID-19 patients." (PMID 41585373, 2025). "Increasing histone acetylation in genes regulating pro-inflammatory cytokines like TNF-α and IL-6 was reported in a group of severe COVID-19 patients." (PMID 40002898, 2025). "Individuals with either flu-like symptoms or infected with COVID-19 residing in EA exhibited higher production of IL-12p70, IL-6, IL-1β, IL-2, and IL-1ra compared to NEA residents." (PMID 40165959, 2025).
COVID-19 (continued). "In COVID-19 and cholestatic liver fibrosis, miR-200c-3p has the potential to negatively regulate IL-6 expression, which is a main component of the cytokine storm." (PMID 40243489, 2025). "Immune dysfunction is pivotal in the development of severe COVID-19, as evidenced by the common observation of higher pro-inflammatory cytokine levels, including IL-6, TNF-α, and IFN-γ, in such cases." (PMID 40137715, 2025). "Acute COVID-19 features an imbalanced host response marked by elevations of IL-1β, IL-6, IL-8, TNF-α and interferon-inducible chemokines (e.g., CXCL9/CXCL10) that govern myeloid recruitment, T-cell positioning, angiogenesis, and tissue remodeling." (PMID 41440526, 2025). "Comorbidities were generally in positive correlation with the clinical outcome, as well as in female COVID-19 patients, while in male COVID-19 patients were positively correlated with IL-6." (PMID 40868247, 2025). "High levels of proinflammatory cytokines, such as TNF-α, IL-1β, and IL-6, produced in severe COVID-19 can reach ocular tissues via the bloodstream, exacerbating local inflammation." (PMID 39861857, 2025). "Beyond glucose metabolism, DPP-4 functions as an immunomodulator; its inhibition reduces inflammatory cytokines (e.g., IL-6, TNF-α) and improves endothelial function, potentially mitigating severe COVID-19–related inflammation and thromboembolic risk." (PMID 40869643, 2025). "A solitary patient with pre-infusion high IL-6 levels from prior sepsis and COVID-19 accounted for the high upper end of the range skewed from the remaining data for all cytokines measured." (PMID 40274761, 2025). "Elevated biomarkers—including NT-proBNP, troponin, and IL-6—have been consistently associated with APE and poor outcomes in COVID-19 cohorts." (PMID 41303223, 2025). "This disruption contributes to the hyperinflammatory response seen in severe COVID-19 cases, which is marked by elevated levels of cytokines such as IL-6, TNF, and IL-1β." (PMID 40431622, 2025). "Meanwhile, it is noted that the significant increase in monocytes producing IL-6 in severe COVID-19 patients suggests that monocytes are key contributors to cytokine storm in COVID-19." (PMID 40723815, 2025). "COVID-19 vaccination significantly improves disease progression, reduces inflammatory marker levels (notably IL-6) and lowers therisk of severe complications, oxygen dependence and mortality." (PMID 41393410, 2025). "Administration of the antiviral drug GS-5734 (remdesivir) and anti-inflammatory therapy reduce the blood level of TMPRSS2 in moderate-course and of IL-6 in severe-course COVID-19." (PMID 40573382, 2025). "IL-6 is one of the pro-inflammatory cytokines released by the immune system in response to an infection, such as viral illnesses like COVID-19." (PMID 40584180, 2025). "Despite mild/no symptoms, significantly elevated cytokine levels, including IL-6, INF-γ, MCP-1, and IL-18 were observed in COVID-19+ pregnancies, associated with distinct hemostasis alterations." (PMID 40303405, 2025). "This hyperactive immune response is characterized by the overproduction of inflammatory cytokines such as IL-6, IL-8, and IL-10, which are notably elevated in severe cases of COVID-19, contributing to immune dysregulation and increased disease severity." (PMID 40497938, 2025). "Elevations in both CRP and IL-6 have, also, been reported in elderly (>62 years old) COVID-19 patients that presented with delirium as well as LC patients with mild–moderate disease course." (PMID 40563736, 2025). "We also observed an increased IL-6 expression by the sweat gland cells in patients of the COVID-19 group." (PMID 40649826, 2025). "In contrast, virtual patients in the COVID-19 reference VPC had the lowest mean IL-6 peak concentrations of 25 pg/ml, which is consistent with reduced severity in otherwise healthy individuals." (PMID 40489562, 2025).